IL6 (interleukin 6)
Diseases named in the same sentence as IL6 in open-access papers (continued):
Sharing a sentence is not in itself a finding about the gene and the disease.
glioblastoma (continued). "It has been shown that quercetin can inhibit IL-6-induced glioblastoma cell growth and migration by regulating the STAT3 signalling pathway, which affects the expression of this protein in glioblastoma cells." (PMID 35971151, 2022). "Cancer-related inflammatory cytokine IL-6 regulates activation of STAT3 and is upregulated in glioblastoma." (PMID 34199460, 2021). "A PTV-loaded nanocarrier was developed to trigger the apoptosis of glioblastoma multiforme cells by reducing the mRNA levels of NFKB, IL6, BIRC1, and BIRC5." (PMID 34925455, 2021). "Here the authors show that IL6 blockade, in combination with a CD40 agonist, overcomes macrophage-mediated immunosuppression and sensitizes glioblastoma to immune checkpoint blockade in preclinical models." (PMID 34103524, 2021). "The mechanism of tumor invasion and immune resistance involving COL6A3, COL1A1, COL1A2, LRRC15, IDO1, IL-6 and PTGS2 need to be further researched aiming to improve prognosis of aggressive glioblastoma." (PMID 33928021, 2021). "Pretreatment plasma IL-6 and YKL-40 and prognosis in newly diagnosed glioblastoma—Multivariate analysis, Full model." (PMID 32363159, 2020). "Like IL-6, OSM feed-forward signaling is observed in aggressive cancers with limited-therapeutic options, including glioblastoma (GBM), non-small cell lung carcinoma (NSCLC), PDAC, and triple negative breast cancer (TNBC)." (PMID 31684144, 2019). "IL-6 was found to be necessary for myeloid PD-L1 induction through a signal transducer and activator of STAT3-dependent mechanism in glioblastoma." (PMID 31192256, 2019). "Here the authors show, in a mouse model of glioblastoma, that endothelial cells in the TME induce macrophage M2 polarization via IL-6 and that depletion of endothelial IL-6 improves survival." (PMID 29422647, 2018). "Vice versa, transfection of the human glioblastoma cell line U-373 MG with a C/EBPD expression vector led to a significant upregulation of C3, CXCL9, CP, CCL3, TNFAIP6, and IL-6 mRNA levels." (PMID 26230261, 2015). "Different types of cyto-chemokines are involved in the crosstalk between hAT-MSCs and BTICs (medulloblastoma and AT/RT: CXCR4/SDF-1, CCR5/RANTES, IL6R/IL-6 and IL8R/IL8; glioblastoma: CXCR4/SDF-1, IL6R/IL-6, IL8R/IL-8 and IGF1R/IGF-1)." (PMID 26076490, 2015). "We observed different expression level of SDF-1, RANTES, IL-6 and IL-8 in medulloblastoma-BTICs, SDF-1, RANTES, IL-6 and IL-8 in AT/RT-BTICs and SDF-1, IL-6, IL-8 and IGF-1 in glioblastoma-BTICs." (PMID 26076490, 2015). "We demonstrated that these glioblastoma cells were put into relatively cytokine "rich" environment produced by AT-MSC containing IL-1β, IL-1ra, IL-2, IL-4, IL-6, IL-8, TNF-α, IFN-γ, CCL5, CCL26, CXCL10, PDGF-bb." (PMID 20509882, 2010). "Overexpression of IL-6, an upstream regulator of STAT3 is also detected in glioblastoma and is a marker of malignancy." (PMID 20712901, 2010). "In glioblastoma multiforme (GBM), the most malignant glioma, amplification/overexpression of the IL-6 gene appears to be a common feature." (PMID 17224923, 2007). "IL-6 from tumor and non-tumor cells in the glioblastoma microenvironment increases tumor-initiating capacity and reduces survival." (PMID 40161763, 2025). "Serotonergic medications may modulate IL-6, activating STAT3 and NF-κB to promote glioblastoma proliferation." (PMID 40894022, 2025). "Rare human glioblastoma patients who achieve clinical responses to ICI have lower pre-treatment IL-6 levels compared to glioblastomas who do not respond to ICI." (PMID 40161763, 2025). "Ketamine has also demonstrated anti-inflammatory potential in vitro, where it was observed to inhibit the production and release of pro-inflammatory cytokines, such as IL-6, IL-1β and TNF-α, in murine macrophages, primary rat microglial cells and human-derived glioblastoma cells." (PMID 40498007, 2025).
glioblastoma (continued). "Additional pathways supporting PMT of glioblastoma cells are induced by hypoxia, necrosis, 17β-estradiol, CXCL12, C5a, bradykinin, and the interleukin (IL)-6 family cytokines, including IL-6, leukemia-inhibitory factor (LIF), and oncostatin M (OSM)." (PMID 39857717, 2025). "Moreover, VPA-treated glioblastoma cells stimulated CAR-T cells to produce higher levels of inflammatory cytokines (IL-2, IFN-γ, and IL-6)." (PMID 39877353, 2024). "It has been reported that combined stimulation of IL-1β, IL-6, and IFN-γ in U373 glioblastoma cell lines and primary human astrocytes could induce APP production and lead to increased Aβ levels." (PMID 39626951, 2024). "Factors such as IL-4/IL-5/IL-6 or IFN-γ/TNF-α/IL-17A in the serum, detectable prior to surgery or GB therapy, may predict the survival of glioblastoma patients." (PMID 37759505, 2023). "Pro-inflammatory cytokines (IL-6), anti-apoptotic proteins from the Bcl-2 family (Bcl-xL), or proteolytic enzymes (MMP-2 and -9) determine the increase of CXCL8-CXCR1/2 protein expression and its promoter activity in glioblastoma cells." (PMID 35269652, 2022). "Activated microglia release interleukin IL-6 and relevant growth factors, including epidermal growth factor (EGF), vascular endothelial growth factor (VEGF), and transforming growth factor-β (TGF-β), which stimulate glioblastoma cell invasion and angiogenesis." (PMID 35885058, 2022). "Previous studies indicated strong overexpression of IL-6, IL-10, VEGF, GM-CSF, and CCL2 in human GBM specimens, and the level of overexpression strongly correlated with tumor grade, proliferation markers, and clinical aggressiveness in glioblastomas." (PMID 35884700, 2022). "Additionally, patients with glioblastoma have constitutively activated STAT3 and secreted IL-6 levels that are correlated with tumor grade." (PMID 36193062, 2022). "In addition, using quercetin-containing nanohydrogels significantly reduced IL-8 production, IL-6 production, and VEGF production in a dose-dependent manner in pro-inflammatory conditions, with meaningful implications for glioblastoma cells’ drug resistance." (PMID 35883021, 2022). "Furthermore, it was evidenced that, in a model of human glioblastoma, the hypoxia-induced accumulation of HIF-1α was correlated with an increase of IL-6 levels." (PMID 33679443, 2021). "Finally, IL6 and IL6R genes were both upregulated in glioblastoma, head and neck, kidney clear cell carcinoma, and testicular cancer." (PMID 34576335, 2021). "One such angiocrine, interleukin-6 (IL-6), has been shown to promote alternative TAM polarization via induction of HIF-2α in glioblastoma, leading to TAM secretion of immunosuppressive molecules, such as TGF-β, IL-10, and Argainse-1, that inhibit T cell activation." (PMID 34987525, 2021). "Pretreatment plasma IL-6 and YKL-40 and patient characteristics for newly diagnosed glioblastoma." (PMID 32363159, 2020). "As PERK is known to regulate the expression of several angiogenic factors such as VEGF-A, IL6 and FGF3,21, we aimed to identify secreted factors that might be involved in PERK-mediated angiogenesis in glioblastoma." (PMID 32054826, 2020). "All these data indicate that IL-6/GP130 signaling plays essential role in the initiation and progression glioblastoma and targeting this pathway may overcome glioblastoma development." (PMID 31942189, 2020). "As IL-6/GP130 inhibitor, bazedoxifene opens a new window for glioblastoma treatment." (PMID 31942189, 2020). "Glioblastomas usually produce several proangiogenic cytokines including VEGF, IL-8, and IL-6." (PMID 30283098, 2018). "Furthermore, IL-6-induced activation of STAT3 have been wildly reported to promote invasion and migration in U251-MG and U87-MG glioblastoma cells." (PMID 28891967, 2017). "Additionally, IL6 siRNA against endogenous IL6 also blocked activation of the IL6-p-STAT3 pathway and hypoxia-induced autophagy in glioblastoma cells." (PMID 27163161, 2016).
glioblastoma (continued). "Co-culture of BTICs and hAT-MSCs showed different expression levels of several cyto-chemokines compared with co-culture of BTICs and HFF1: SDF-1, RANTES, IL-6 and IL-8 in medulloblastoma-BTICs, SDF-1, RANTES, IL-6 and IL-8 in AT/RT-BTICs and SDF-1, IL-6, IL-8 and IGF-1 in glioblastoma-BTICs." (PMID 26076490, 2015). "Thus, targeting cytokine IL-6 and stimulating CD40 to expose the glioblastoma to an immune checkpoint blockade, together may mitigate tumor antigen-mediated immune suppression while maintaining T cell infiltration in glioblastoma." (PMID 38892305, 2024). "When the effect of CRT on IFN-γ, IL6, and TNFα was investigated for patients with locally advanced non-small-cell lung cancer (NSCLC) or glioblastoma multiforme (GBM), TNF-α levels in NSCLC and IFN-γ levels in GBM decreased." (PMID 38534922, 2024). "RT-treated patients with low ARID1A expression from other tumor entities, such as skin cutaneous melanoma (SKCM), thyroid carcinoma (THCA), and glioblastoma multiforme (GBM), displayed higher expression of CXCL10, IL-6 and CXCL9." (PMID 38587186, 2024). "The best method to evaluate the hypothesis is a proposed, scientifically rigorous, phase II trial that would use VNS, exploiting the “inflammatory reflex,” to reduce IL-6 levels systemically, and in combination with ICI, create an immune responsive TME in patients with glioblastoma." (PMID 39512605, 2024). "Molecular markers of glioblastoma such as methylated O6-methylguanine-DNA methyltransferase (MGMT) promoter methylation was seen in 16 out of the 33 patients evaluated (48%) and expression of immunological markers such as TNF-a, IL-1β, and IL-6 was considered in one patient." (PMID 38137175, 2023). "There, genes with a higher expression in glioblastoma compared to astrocytoma were VEGFA, 4EBP1, CCL2, PLAU (uPA), CXCL8 (IL8), CXCL10 (IP10), CASP8, HGF, LIF, CD40, CDCp1, TNFRSF11B (OPG), CD274 (PD-L1), IL6, CXCL1, CCL20 (MIP3α), CCL8 (MCP2), CD244, MMP1, TNFRSF9, CXCL6, MMP10, FGF5)." (PMID 35301393, 2022). "STAT3 activation by US28-mediated IL-6 secretion was also reported to be involved in VEGF production in NIH-3T3 cells stably transfected with US28 and U373MG cells 48 h after infection with HCMV as well as in primary glioblastoma specimens from patient samples." (PMID 32779712, 2020). "However, the spheroids formed by TRAF3IP2-silenced U87 cells (U87TRAF3IP2KDversus U87control shRNA cells) expressed markedly reduced VEGF, IL-17R, IL-1β, IL-6, and IL-8 expression, further demonstrating a pro-angiogenic and pro-inflammatory role of TRAF3IP2 in glioblastoma cells." (PMID 30038719, 2018). "Therefore, during glioblastoma-induced inflammatory responses, the interaction among albumin, IGFBP-2 and IL-6 may greatly affect clinical outcomes." (PMID 25880463, 2015). "Indeed, our data and data from other investigators suggest that the survival benefit from IL-6 plus ICI blockade is modest, but when combined with additional agents, such as CD40 stimulation or radiotherapy, this therapeutic strategy can durably prolong survival in glioblastoma preclinical models." (PMID 40161763, 2025). "Interestingly, some NSAIDs like aspirin could not only cancel the pro-tumorigenic effects of IL-6 but also downregulate the IL-6-STAT3 signaling pathway to induce cancer cell apoptosis, which have been validated in colorectal cancer and glioblastoma A172 cells." (PMID 37986068, 2023). "Moreover, glioblastoma-derived EVs may skew the differentiation of peripheral blood monocytes to alternatively activated M2 macrophages inducing the expression of elevated levels of VEGF, IL6, Cox2, ARG1, and PD-L1 through STAT3 activation." (PMID 31447834, 2019). "Emerging work using spatial protein profiling of human glioblastoma tissue samples paired before and after exposure to ICI has identified enrichment in IL-6 and its downstream effectors in ICI nonresponders." (PMID 41392975, 2025).
glioblastoma (continued). "ICI non-responders were enriched in glioblastoma stem cells marked by SOX2 and PTPRZ1 and in cells marked by the IL-6 effector p-STAT3 in both pre- and post-ICI samples compared to ICI responders." (PMID 40161763, 2025). "IL-6 signaling in human glioblastoma patients after treatment with ICI has not been investigated, and the impact of IL-6 blockade on the glioblastoma TIME and its potential synergy with ICI or other adjuvant therapies are incompletely understood." (PMID 40161763, 2025). "Indeed, in patient-matched human glioblastomas pre- and post-ICI, spatial transcriptomic profiling demonstrated IL-6 suppression in pre-ICI samples from ICI responders compared to pre-ICI samples from non-responders, suggesting that reduced IL-6 may facilitate glioblastoma responses to ICI." (PMID 40161763, 2025). "Furthermore, survival was longer in the Il-6 knockout mice relative to wild-type mice, which was not the case when SB28 glioblastoma was implanted into C57BL/6J Ccl2 or Cxcl10 knockout mice." (PMID 40161763, 2025).
malaria (249 papers, 2008 to 2026). Malaria is a serious and sometimes fatal disease caused by a parasite that commonly infects a certain type of mosquito which feeds on humans. "The modulation of TNF-α and IL-6 by potential therapeutic agents is of significant interest in developing effective treatments for malaria-associated complications." (PMID 40917784, 2025). "Immune cells produce IL-6 when infected with malaria parasites, and this has been associated with the immunopathogenesis of malaria." (PMID 39204168, 2024). "For example, one of the significant PBS values was interleukin-6 (IL6), which encodes interleukin-6 and is the indicator of malaria severity, which was selected in the Sui, Jing, Miao, and Zhuang groups." (PMID 38448908, 2024). "It has been observed that clinical or severe malaria is associated with increased levels of pro-inflammatory cytokines, including IL-1β, IL-6, IL-8, IL-10, IL-12, IL-13, IL-31, IL-33, and TNF-α." (PMID 39204168, 2024). "IL-6 has been implicated as a candidate marker for severe malaria, as its levels were increased in severe malaria compared to uncomplicated malaria." (PMID 36716305, 2023). "Although TNF, IL-6, and IL-12 are proinflammatory cytokines associated with severe malaria, their levels have been reported to be decreased in malaria and HBV coinfections." (PMID 36716305, 2023). "TNF, IFN-γ, IL-6, and IL-12 are proinflammatory cytokines associated with malaria infection and severe malaria." (PMID 36716305, 2023). "Subsequently, we then used these SNPs in the MR analyses to estimate the causal effect of IL-6 signaling on severe malaria." (PMID 36801374, 2023). "IL-6 has often been associated with increased severity during malaria caused by P. vivax in Brazil’s extra-amazon and Amazon regions however this cytokine has not yet been evaluated in this scenario of malaria coinfection with enteric pathogens." (PMID 35749690, 2022). "It has been reported that profound levels of pro-inflammatory cytokines, such as TNF-α and IL-6 are associated with severe malaria." (PMID 35214662, 2022). "The last gene with significant PBS signals was IL6 which encodes interleukin-6 and is one of the indicators of malaria severity." (PMID 36173765, 2022). "Interleukin-6 (IL-6) is generated by immune cells during infection with malaria parasites and they are associated with the immunopathogenesis of malaria." (PMID 35396564, 2022). "IL-8 mediates neutrophil trafficking and IL-6 has a “pleiotropic effect on inflammation, immune response, and hematopoiesis” as well as has been associated with acute phase response in malaria." (PMID 33424841, 2020). "Studies have shown that increasing levels of TNF-α and IL-6 in malaria are associated with the cytoadherence of infected erythrocytes leading to the development of febrile disease." (PMID 33281757, 2020). "TNF-α and IL-6 are both proinflammatory cytokines, which are associated with the severity of malaria." (PMID 31878288, 2019). "In humans, IFN-γ levels to schistosome egg and worm antigen has been found to decrease during pregnancy and high IL-10 levels as well as IFN-γ, TNF-α, IL-10 and IL-6 have been found to be associated with pregnancy associated malaria." (PMID 29970128, 2018). "Elevated levels of IL-6 have also been associated with an increase in the incidence of clinical malaria." (PMID 29970128, 2018). "The response of anti-inflammatory cytokines such as IL-10 and IL-10/TNF-α, IL-10/IFN-γ and IL-10/IL-6 ratios in clinical malaria caused by P. vivax was short-lived and positively correlated with parasitemia rather than with the symptoms." (PMID 28243235, 2017). "Inflammatory cytokines such as tumour necrosis factor- α (TNF-α), interleukin-1 (IL-1) and IL-6, have been described to correlate with severe malaria but the major role of TNF-α has been linked with parasite killing." (PMID 29034874, 2017).